CMTM6 (CKLF like MARVEL transmembrane domain containing 6)
Diseases named in the same sentence as CMTM6 in open-access papers (continued):
Sharing a sentence is not in itself a finding about the gene and the disease.
tumor (continued). "CMTM6 depletion significantly reactivated tumor-specific T cells via reducing PD-L1, indicating that CMTM6 could be a new drug target to enhance efficacy of checkpoint blockade." (PMID 35372044, 2022). "Based on previous studies and our results, we speculate that CMTM6 may activate the transmission of related signals in the PD-L1 pathway or enhance the secretion of some cytokines in the tumor immune response, thus promoting the progression of GC." (PMID 33509216, 2021). "One possible mechanism is that CMTM6 binds with PD-L1 protein, decreases its ubiquitination and increases the half-life of PD-L1 protein, resulting in enhanced ability of tumor cells to inhibit T cells; the elimination of CMTM6 would reduce PD-L1 and improve OS." (PMID 33509216, 2021). "The tumor tissues had elevated levels of CMTM6, CMTM4, and CD274 (PD-L1) transcripts." (PMID 34680324, 2021). "In addition, depletion of CMTM6 delays tumor growth, enhances tumor-specific T cell activity and reduces the number of exhausted T cells." (PMID 34867972, 2021). "Through immunofluorescence and cell fractionation assays, we found that CMTM6 and PD-L1 were mainly co-localized in the cell membrane and cytoplasm of GC tumor cells, and the expression of CMTM6 and PD-L1 in GC cell lines was higher compared with levels in GES-1 cells." (PMID 33509216, 2021). "Similar to PD-L1, CMTM6 was expressed in both CRC tumor cells (TCs) and interstitial ICs." (PMID 33818637, 2021). "Collectively, the tissue array data demonstrated that CMTM6 expression is associated with poor prognosis irrespective of epithelial or mesenchymal regions, while the association of CMTM4 and prognosis is more restricted to tumor epithelial region." (PMID 34680324, 2021). "High expression of CMTM6 has been found to correlate with poor prognosis in several types of tumor." (PMID 34680324, 2021). "CMTM6 mRNA levels in >10,000 tumor and normal tissue samples were analyzed from the TCGA cohort." (PMID 33552963, 2020). "Furthermore, we evaluated the immune score of patients with tumor from the TCGA cohort using the ESTIMATE algorithm and found that high CMTM6 expression was associated with higher immune infiltration score in most tumors." (PMID 33552963, 2020). "We speculate that CMTM6 expression may play a role in regulating tumor cells by inducing neutrophil infiltration." (PMID 33552963, 2020). "Additionally, we investigated CMTM6 protein expression from the HPA cohort, which presented CMTM6 protein expression in 14 different tumor types." (PMID 33552963, 2020). "In HCC, CMTM6 expression of mRNA in tumor samples was significantly lower than in normal samples." (PMID 33282744, 2020). "Thus, CMTM6 depletion, via the reduction of PD-L1, significantly alleviates the suppression of tumor-specific T cell activity in vitro and in vivo." (PMID 29910728, 2018). "In accord, ablation of CMTM6 in mouse cancer models was shown to efficiently suppress tumor growth, but unexpectedly in a manner partially independent of PD-L1, suggesting that CMTM6 may regulate additional proteins involved in anti-tumor immunity." (PMID 41634378, 2026). "Furthermore, exosomal CMTM6 activates the mTOR signaling pathway in tumor-associated macrophages, enhancing CCL2 secretion, which further promotes M2a polarization and accelerates tumor metastasis." (PMID 40761779, 2025). "For instance, CMTM6-mediated stabilization of PD-L1 can inhibit the activation of cytotoxic NK cells and impair the antigen-presenting function of dendritic cells, further promoting an immunosuppressive microenvironment conducive to tumor growth and progression." (PMID 40191195, 2025). "Interestingly, CMTM6 has been found to stabilize nuclear P21 leading to inhibited tumor growth." (PMID 39335098, 2024). "In addition, CMTM6 expression has been detected in several healthy tissues, and it may have functions other than triggering immune evasion by tumor cells." (PMID 38223763, 2024).
tumor (continued). "This suggests that CMTM6 may be a potential new target for tumor immunotherapy." (PMID 38495487, 2024). "Additionally, reduction of CD58 expression by shRNA to the same level as observed in CMTM6-knockout cells resulted in a slightly more pronounced attenuation of T cell activation and improved the tumor cell survival compared to that observed in CMTM6-knockout cells." (PMID 37683639, 2023). "Although CMTM6 plays an important role in the TME, the regulatory pathways for CMTM6/4 in regulating different components of TME are complicated and vary in different tumor microenvironments which implicated that the effect of CMTM6/4 on TME might be cancer type dependent." (PMID 35958549, 2022). "Results showed that there is a significant association between CMTM6 expression and Ki67 expression/recurrence, while CMTM4 expression is not significantly different between patients with clinically-related factors, indicating that CMTM6 may play an important role in tumor genesis and development." (PMID 35983975, 2022). "Moreover, inversely regulation of p21 could block the suppressing effects of CMTM6 on HCC cells, confirming that CMTM6 functioned as a tumor suppressor mainly by acting on p21." (PMID 35304440, 2022). "Therefore, as CMTM6 facilitates tumor cells for immune evasion and mediates cisplatin resistance, it could be a promising therapeutic target for treating therapy-resistant OSCC." (PMID 33434185, 2021). "Targeting CMTM6 restores EGFR degradation, suppresses tumor growth, and confers therapeutic benefit in both CDX and PDX models, offering a promising strategy against TKI‐resistant NSCLC." (PMID 40521789, 2025). "Using multiplexed Opal fluorophores, we simultaneously evaluated five markers: CMTM6, EGFR, RAB11, DAPI (a nuclear dye), and Pan Cytokeratin (to discern tumor versus stromal cell identity)." (PMID 40521789, 2025). "The results showed reducing CMTM6 levels led to decreased glycolysis of CRC cells, CRC tumor growth and liver metastasis in mice." (PMID 39218981, 2024). "Elevated CMTM6 expression correlates with poor prognosis in NSCLC, likely fueling tumor progression by stabilizing PD-L1 on tumor cells." (PMID 38495487, 2024). "CMTM6 is a regulator of PD-L1 expression and plays an important role in the TME via its expression in both tumor and immune cells." (PMID 39630300, 2024). "IHC analysis revealed widespread and largely overlapping expression of CMTM6 and CD58 in tumor cells in samples of both cancer types." (PMID 37683639, 2023). "In this study, we found that CMTM6 (CKLF like MARVEL transmembrane domain containing 6) plays a key role in promoting the expression of both CD58 and PD-L1, two immune checkpoint ligands with opposing functions, in tumor cells." (PMID 37683639, 2023). "In their xenograft C3H/He mice models, depletion of CMTM6 significantly increased the infiltrating proportion of T cells (CD4+ and CD8+ T cells) in tumor." (PMID 35958549, 2022). "In summary, CMTM6 and CMTM4 play important roles in the TME through regulating PD-L1, immune cells, tumor cells and different components of TME." (PMID 35958549, 2022). "qPCR and Western blot analysis in HCC tissues confirmed that CMTM6 mRNA and protein expression were downregulated in HCC tumor tissues compared with that in paired normal liver tissues." (PMID 35304440, 2022). "CMTM6 and CMTM4 are novel proteins found to promote tumor progression by stabilizing PD-L1 in recent and ongoing research." (PMID 35958549, 2022). "The roles of CMTM6 and CMTM4 in regulating TME components, including immune cells and tumor cells themselves were discussed in this review." (PMID 35958549, 2022). "Indeed, our results demonstrate that the co-expression of CMTM6 or CMTM4 with PD-L1 on the membrane of tumor cells is critical for immunotherapeutic response and the pathological patterns of their expression may provide detailed information to conduct personalized immunotherapy." (PMID 34680324, 2021).
tumor (continued). "Compared to each molecule alone, the co-expression of CMTM6 and PD-L1, CMTM6 and CMTM4 in the tumor epithelial region showed better prognostic value in the patients with GC." (PMID 34680324, 2021). "Therefore, because CMTM6 expression has been detected in several tissues, it is predicted that it might have several biological functions other than triggering immune evasion by tumor cells." (PMID 33434185, 2021). "The expression of CMTM6 was downregulated and was correlated with the AFP level and tumor metastasis of HCC patients." (PMID 32874775, 2020). "They found that CMTM6 was in a lower expression level in HCC, and which correlated with tumor metastasis and low survival of patients." (PMID 33282744, 2020). "Histological revealed higher CMTM6 expression in HCC tissues than in adjacent normal tissues, and its expression correlates with metastasis, tumor staging and the expression of alpha-fetoprotein." (PMID 31754330, 2019). "Thus, RNASEH2C advanced tumor progression by promoting RAI14 lysosomal degradation, with HSC70 and CMTM6 playing key roles." (PMID 41361104, 2025). "In addition, tumor tissues were stained with H&E to observe tumor cell morphology, and immunohistochemistry (IHC) was performed to detect the expression level of p21, WWP2, CMTM6, the cell cycle promoter c-MYC, and the proliferation marker PCNA." (PMID 41387673, 2025). "Notably, the expression levels of CMTM6 and EGFR within whole cells, on the cell membrane, and in the cytoplasm, all exhibited a significant elevation in tumor areas compared to the adjacent stromal tissue." (PMID 40521789, 2025). "Then, WB and IHC analysis both revealed that CMTM6 expression was higher in tumor tissues than matched non-tumor tissues." (PMID 40761779, 2025). "The absence of CMTM6 significantly hinders the recruitment and infiltration of TAMs, thereby suppressing tumor development and progression." (PMID 40761779, 2025). "CMTM6, a noncharacteristic protein on the cell surface, is located in a region rich in tumor suppressor genes." (PMID 38223763, 2024). "Our study revealed heightened CMTM6 expression in NSCLC and its presence in macrophages, lymphocytes, and bronchial epithelial cells in adjacent normal lung tissues, indicating its role in tumor progression." (PMID 38495487, 2024). "Using digital image analysis, membranous and/or cytoplasmic CMTM6 positivity in tumor cells predicted a shorter OS independent of other clinicopathological parameters." (PMID 38067301, 2023). "Moreover, we individually quantified the protein expression levels of CMTM6 and CD58 on tumor cells based on the IHC analysis." (PMID 37683639, 2023). "CMTM6 protein expression was very low or nearly undetectable in 6 non-tumor breast tissues and negative, weak, moderate and strong CMTM6 expression were detected in 14, 15, 23 and 24 HER2+ BC tissues, respectively." (PMID 36627608, 2023). "Additionally, CMTM6 is a critical regulator of PD-L1 stability in a broad range of cancer cells, and dual inhibition of HER2 and PD-L1 successfully enhances the anti-tumor effect of anti-HER2 monotherapy in HER2-positive tumor cell." (PMID 37174034, 2023). "Given the dual roles of CMTM6 in maintaining the cell surface expression of both CD58 and PD-L1, we sought to determine the relative importance of these two immune checkpoints with opposing functions in T cell-tumor cell interactions." (PMID 37683639, 2023). "Despite these limitations, our study not only contribute to our understanding of the role of CMTM6 in tumor growth in HCC, but will also lead to the characterization of a specific HCC patients’ group with CMTM6 overexpression who may benefit from TACE." (PMID 35304440, 2022). "In another TMA cohort consisting of 47 HCC cases with portal vein embolus, CMTM6 expression was not significantly different between primary lesions and tumor embolus metastases." (PMID 32770259, 2021).
tumor (continued). "Elevated expression of CMTM6 was frequently accompanied with worse malignant phenomenon, such as with high AFP level, large tumor size, advanced TNM stage, vascular invasion in a large cohort of 619 HCC cases (In Zhu’s study, only 75 HCC samples were collected)." (PMID 32770259, 2021). "Based on real-time quantitative PCR (qRT-PCR) and IHC analysis, higher abundance of CMTM6 was observed in tumor tissues of nonresponders as compared with responder OSCC patients." (PMID 33434185, 2021). "shRNA-based depletion of CMTM6 in cisplatin-resistant cells and in vivo patient-derived cell (PDC1) xenograft models restored drug-induced apoptosis as evident from substantial reduction of tumor burden." (PMID 33434185, 2021). "Conversely, the expressions of CMTM6 and PD-L1 were not related to patient age, sex, tumor size, tumor differentiation, tumor location, or T stage." (PMID 33509216, 2021). "Moreover, SHMT2 is involved in some processes of tumorigenesis and is related to PD-L1, CMTM6, VISTA, B7-H4, Slug, and CD317 expression in the tumor microenvironment of OSCC." (PMID 33163414, 2020). "Expression of CMTM6 can affect the presence of programmed death ligand-1 (PDL1/CD274) at the surface of cells in a tumor environment at least in vitro, a possible mechanism to regulate anti-tumor immunity." (PMID 32908139, 2020). "To explore whether CMTM6 regulates CRC tumor growth via a mechanism independent of PD-L1-mediated cancer immune evasion, we generated control and CMTM6-knockdown CRC cells and compared their proliferation in vitro." (PMID 39218981, 2024). "However, unlike other family members, CMTM6 exhibits a 'cancer-promoting' effect by stabilizing PD-L1 molecules on tumor cell surfaces, consequently hindering the anticancer immune response of T cells." (PMID 38495487, 2024). "The interaction of CMTM6 with other tumor-infiltrating cells has not been reported." (PMID 36643629, 2023). "Since genotoxic agent treatment can induce p21 upregulation but has no influence on the levels CMTM6, we speculate that the expression levels of CMTM6 but not p21 in the initial tumors might be a potential biomarker to reflect the sensitivity of tumor to TACE." (PMID 35304440, 2022). "However, the expression of CMTM6 in TCs and ICs was not linked with CD4+ or CD8+ tumor-infiltrating lymphocyte density in either dMMR or pMMR CRC." (PMID 33818637, 2021). "Finally, CMTM6 expression in either tumor or stroma was not correlated with prognosis in patients with NSCLC." (PMID 34065396, 2021). "Unlike pattern 1, the intensity of CMTM6 and CMTM4 expression in pattern 2B was lower and was mainly found in the cytoplasm of tumor epithelial cells." (PMID 34680324, 2021).
cancer (54 papers, 2019 to 2026). A tumor composed of atypical neoplastic, often pleomorphic cells that invade other tissues. "CMTM6 holds potential as both a biomarker for assessing the future risk of CC and a therapeutic target in cancer treatment." (PMID 40761779, 2025). "The role or roles of exosome-associated CMTM6 in other cancers and with respect to exhaustion in cytotoxic cell populations or response to immune checkpoint blockade have yet to be explored." (PMID 39335098, 2024). "Of these targets, CDCP1 is reportedly associated with PI3K/AKT signaling, CMTM6 is a critical regulator of PD-L1 in a broad range of cancer cells, while UBE2D3 is linked to NF-κB signaling and ADAM10 plays a role in TNF signaling." (PMID 38041015, 2023). "On one hand, overexpression of CMTM6 is associated with malignant molecular and clinical characteristics, and is linked to worse prognosis in several cancers, such as glioma and oral squamous cell carcinoma." (PMID 37174034, 2023). "CKLF like MARVEL transmembrane domain containing 6 (CMTM6) has been associated with the development in many kinds of cancers." (PMID 33757532, 2021). "Several studies indicated that CMTM6 expression correlated positively with PD-L1 expression and was associated with poor prognosis of various cancers." (PMID 33757532, 2021). "The results suggested that CMTM6 expression was associated with high immune infiltration in some cancer types." (PMID 33552963, 2020). "High CMTM6 expression was associated with expression of immune checkpoint-associated genes and poor prognosis in diverse prevailing cancers." (PMID 33552963, 2020). "In this present study, we comprehensively analyzed the association between CMTM6 expression and the immune microenvironment and investigated its correlation with pan-cancer prognosis." (PMID 33552963, 2020). "This study also revealed that CMTM6 expression may be positively correlated with inflammatory responses and somatic mutations that promote cancer progression." (PMID 38223763, 2024). "CMTM6 has been associated with the development of a variety of cancers." (PMID 38223763, 2024). "Other research groups have been examining the interaction of CMTM6 with PD-L1 in cancer cells; they revealed that CMTM6 associates with PD-L1 on the cell surface, reduces its ubiquitination, increases the half-life of PD-L1, and acts to exacerbate anticancer immunity." (PMID 36869893, 2023). "Therefore, an increasing amount of research is focused on the interaction and association involving CMTM6 and PD-L1 in many cancers and even some inflammatory diseases." (PMID 37726578, 2023). "Despite the well-established role of CMTM6 in the stabilization of cell surface PD-L1 in cancer cells, the mechanisms underlying CMTM6 expression and regulation are still largely unknown." (PMID 33649535, 2021). "Interestingly, we found that high CMTM6 expression was positively associated with neutrophil infiltration in 14 cancer types." (PMID 33552963, 2020). "Increased CMTM6 expression may be associated with increased infiltration of neutrophils in some types of cancer." (PMID 33552963, 2020). "A high CMTM6 expression was associated with reduced survival time and may be a strong indicator of poor prognosis in different cancer types." (PMID 32874775, 2020). "Altogether, our findings urge caution when translating promising data regarding the targeting of CMTM6 from mouse cancer models to potential human therapies." (PMID 41634378, 2026). "In 2017, CMTM6 is co-localized with PD-L1 at the plasma membrane, and can increase PD-L1 protein half-life through reducing PD-L1 ubiquitination in cancer cells." (PMID 40179060, 2025). "In fact, a literature search indicates that this is the first time, to the best of our knowledge, that increased CMTM6 in the plasma of patients with any cancer has been reported." (PMID 39335098, 2024).